CCN2 (cellular communication network factor 2)
Diseases named in the same sentence as CCN2 in open-access papers (continued):
Sharing a sentence is not in itself a finding about the gene and the disease.
glaucoma (46 papers, 2013 to 2025). Increased pressure in the eyeball due to obstruction of the outflow of aqueous humor. "Exogenous expression of CCN2 causes glaucoma in mice by modifying the actin cytoskeleton of the trabecular meshwork." (PMID 25879570, 2015). "Furthermore, CCN2/CTGF is associated with fibrosis, extracellular matrix remodeling, and glial activation; processes that are prevalent in both glaucoma and neurodegeneration." (PMID 41009668, 2025). "The eye specific overexpression of CCN2/CTGF caused an increase in IOP and led to a loss of axons, the hallmark of primary open-angle glaucoma." (PMID 37251082, 2023). "Increased concentrations of CCN2/CTGF are reported in the aqueous humor of various glaucoma forms and the lens specific overexpression of CCN2/CTGF causes elevated IOP and a decline of ON axons in transgenic mice." (PMID 37251082, 2023). "CCN2/CTGF is constitutively expressed by cells of the TM and its levels were reported to significantly increase in the aqueous humor of glaucoma patients compared to control individuals." (PMID 32429045, 2020). "Matricellular proteins CCN2 and THBS found altered at high frequency in our study are important modulators of fibrosis and also implicated in glaucoma as causing increased ECM deposition in the trabecular meshwork." (PMID 25879570, 2015). "Furthermore, the identification of DEGs, such as TTBK1 and CTGF/CCN2, which are implicated in neurodegenerative pathways, supports the biological overlap between glaucoma and diseases like Alzheimer’s." (PMID 41009668, 2025). "We analyzed the effect of CCN2/CTGF in vivo in our transgenic glaucoma mouse model." (PMID 37251082, 2023). "The pathologic effect of TGF-β2 in primary open-angle glaucoma is mainly meditated by CCN2/CTGF." (PMID 37251082, 2023). "Increased CCN2 production is reported in rabbit model of glaucoma filtration surgery." (PMID 25879570, 2015). "We conclude that CCN2/CTGF functions as a modulator of the homeostatic balance of BMP and TGF-β signaling pathways, which is shifted in primary open-angle glaucoma." (PMID 37251082, 2023). "Interestingly, we could observe enhanced levels of TGF-β1 and TGF-β2 in the transgenic βB1-CTGF1 mice accompanied by increased TGF-β signaling in the outflow tissues, which would make CCN2/CTGF of interest for pathological effects in both pseudoexfoliation glaucoma and POAG patients." (PMID 37251082, 2023). "In this study we analyzed the astrocytic reactivity and CCN2/CTGF level in the ON and ONH and the ECM protein synthesis in the peripapillary sclera in the βB1-CTGF1 murine glaucoma model." (PMID 35493079, 2022). "Elevated levels of CCN2 and THBS have been reported in aqueous humor as well as in the trabecular meshwork of glaucoma patients and in other fibrotic conditions." (PMID 25879570, 2015). "Nevertheless, we strongly believe that all these results make DCN an interesting candidate for future treatments of glaucoma due to its ability to reduce expression and synthesis as well as activity of TGF-β and CTGF/CCN2 in human and murine astrocytes of the ON and ONH." (PMID 34299278, 2021).
gastric cancer (42 papers, 2011 to 2026). A primary or metastatic malignant neoplasm involving the stomach. "Other studies reported a downregulation of Cyr61/CCN1 and CTGF/CCN2 expression by 2 μM VP during longer treatment in gastric cancer and glioma cell lines." (PMID 37877098, 2023). "After CCN2 downregulation, gastric cancer cells show attenuated migratory/invasive abilities and decreased protein expression of MMPs." (PMID 33833779, 2021). "In gastric cancer, high CCN2 expression correlates with more lymph node metastases, more peritoneal dissemination, and poorer 5-year survival." (PMID 33833779, 2021). "In chondrosarcoma cells, CCN2/CTGF enhances cell migration by matrix metalloproteinase-13 upregulation through integrin α5β3 and in gastric cancer through downregulation of E-cadherin by NF-κB pathway." (PMID 25120383, 2014). "Differential expression analysis showed that IGFBP7, CCN2, ESM1, CCN4 and CCN6 mRNA were over-expressed in gastric cancer tissues while CCN5 mRNA was down-expressed (all p < 0.05)." (PMID 37304887, 2023). "From overall survival analysis, gastric cancer patients with high expression of IGFBP7, CCN2, CCN3, CCN1, CCN5 or CCN4 would have a poor survival time (all p < 0.05)." (PMID 37304887, 2023). "The 5-year survival of CCN2/CTGF-high stomach cancer patients was 18%, while that of the CCN2/CTGF-low expression group was 50%." (PMID 32260433, 2020).
glioma (41 papers, 2008 to 2024). A benign or malignant brain and spinal cord tumor that arises from glial cells (astrocytes, oligodendrocytes, ependymal cells). "It has been shown that CCN1, CCN2, and CCN4 all contribute to glioma progression, in agreement with our findings." (PMID 36589241, 2022). "It was shown that miR-375 might be able to inhibit glioma growth by repressing the Cellular Communication Network factor 2 (CCN2 or CTGF)-epidermal growth factor receptor signaling pathway, resulting in the reduction of glioma proliferation, migration and invasion." (PMID 39684236, 2024).
Hyperglycemia (40 papers, 2012 to 2025). An increased concentration of glucose in the blood. "In the present study, we did not observe any loss of phenotype after the cells were subjected to a combination of a lower concentration of TGF-β1 in the presence of hyperglycaemia, suggesting PTECs retained their epithelial phenotype at the time of CCN2 production and secretion." (PMID 34003249, 2021). "Indeed, chronic hyperglycaemia is known to up-regulate various pro-fibrotic genes in the diabetic heart as a whole, including Col1a1, Postn, Timp-2 and Ccn2." (PMID 34074290, 2021). "Therefore, we demonstrated that STAT3 activation and expression of CCN2 and fibronectin are enhanced by hyperglycemia in the heart both in vivo and in vitro." (PMID 28672855, 2017). "Other metabolic factors such as hyperglycemia, reactive oxygen species, advanced glycation end products (AGEs), and free fatty acids induce CCN2/CTGF expression in affected tissues." (PMID 32429045, 2020). "By 6 months after the onset of hyperglycemia, STZ mice showed visible accumulation of collagen in the upper (3.5-fold; p = 0.001) and lower lobes (4.3-fold; p < 0.0001) of the lung, along with a significant increase in mRNA expression of Acta2 and Ccn2." (PMID 37819895, 2023). "In vitro, increased CCN2 mRNA expression or protein production was shown to result from the exposure of cultured Day 4 primary rat HSC to glucose or insulin to mimic, respectively, the hyperglycemia or insulin resistance that are frequently seen in NASH patients." (PMID 37629004, 2023). "Thus, mechanical factors typified by stiffness, tension, shear stress, stretch, and hydrostatic pressure and chemical stimuli such as hypoxia, hyperglycemia and hyperlipidemia might be the primary inducers of the CCN2/CTGF gene in vivo." (PMID 32429045, 2020). "Although hyperglycemia occurs in some NASH models, blood glucose levels were significantly decreased in WT mice on the CDAA-HF diet for 8 weeks, but there was no change in Alb-CCN2 TG mice." (PMID 37629004, 2023).
hepatocellular carcinoma (39 papers, 2011 to 2025). A malignant tumor that arises from hepatocytes. "Overexpression of CCN2 also has been shown to induce the upregulation expression of Wnt/β-catenin transcriptional target genes, and our group also proved CCN2 was associated with the Wnt signaling activation in hepatocellular carcinoma (HCC)." (PMID 33833779, 2021). "By cDNA microarrays, we also found oxaliplatin-pretreated hepatocellular carcinoma exhibited the enhanced stemness and increased expression of CCN2 and LRP6." (PMID 28870205, 2017). "In the present study, we confirmed the increased expression of CCN2 in oxaliplatin-resistant hepatocellular carcinoma with enhanced stemness." (PMID 28870205, 2017). "Another study reported that tumor-derived CCN2/CTGF could mediate tumor–stromal interactions which accelerate hepatocellular carcinoma progression." (PMID 32260433, 2020). "The results of the previous studies are not consistent with the data of the present study and showed that S1P enhances the proliferation of hepatocellular carcinoma cells by upregulating the expression of CCN2 via the S1P2-mediated intracellular signaling pathway." (PMID 31731760, 2019). "However, when the expression levels of CCN2 and CCN3 in the same cases of hepatocellular carcinoma were compared, induction and reduction of the expression of CCN3 and CCN2, respectively, were observed, indicating the retention of the yin–yang regulatory system in these particular cases." (PMID 35682564, 2022). "Likewise, LRP6 was found in hepatocellular carcinoma (HCC) whereby oxaliplatin-pretreated hepatocellular carcinoma showed the improvement of its stemness and increased expression of LRP6 and connective tissue development factor (CCN2)." (PMID 31031810, 2019).
idiopathic pulmonary fibrosis (39 papers, 2009 to 2025). Idiopathic pulmonary fibrosis (IPF) is a nonneoplastic pulmonary disease that is characterized by the formation of scar tissue within the lungs in the absence of any known cause. "Consequently, FG‐3019 (Pamrevlumab), which is a humanized anti‐CCN2 monoclonal antibody, was used in clinical trials for the treatment of idiopathic pulmonary fibrosis (IPF) in the USA." (PMID 41019779, 2025).
osteosarcoma (39 papers, 2006 to 2025). A usually aggressive malignant bone-forming mesenchymal neoplasm, predominantly affecting adolescents and young adults. "Therefore, CCN2 expression is associated with a chemoresistant phenotype of osteosarcoma cells." (PMID 24637722, 2014). "Mechanistically, the forced expression of miR-584-5p hindered the proliferation and motility of osteosarcoma cell lines by directly targeting the 3′UTR of CCN2 (also known as CTGF)." (PMID 39000555, 2024). "CCN2 promotes osteosarcoma cell migration by downregulating miR-519d and upregulating MMP-2 and MMP-3." (PMID 34228239, 2021). "Here, we show that overexpressing CCN2 in human osteosarcoma cells enhanced resistance to cisplatin through inhibiting cisplatin-induced apoptosis and promoting tumor cell survival." (PMID 24637722, 2014). "In conclusion, we showed that cisplatin-induced CCN2 expression in osteosarcoma cells promoted cell survival ability, which inhibited apoptosis and increased resistance from cisplatin treatment." (PMID 24637722, 2014). "Taken together, we suggest that CCN2 plays an important role in osteosarcoma progression by supporting tumor cell survival and drug resistance." (PMID 24637722, 2014). "In contrast, decreased CCN2 expression promoted cisplatin-induced apoptosis of cells in osteosarcoma." (PMID 24637722, 2014). "Our in vitro and in vivo xenograft studies showed that overexpressing CCN2 significantly increased tumor cell survival, and suppression of CCN2 expression significantly increased drug sensitivity of osteosarcoma cells." (PMID 24637722, 2014). "According to these results, Bcl-xL and survivin are important downstream effectors in CCN2-enhanced resistance from cisplatin-mediated cell apoptosis in osteosarcoma cells." (PMID 24637722, 2014). "Here, we found that CCN2 was upregulated in human osteosarcoma cells after treatment with cisplatin." (PMID 24637722, 2014). "Incubation of osteosarcoma cell lines with cisplatin significantly increased CCN2 protein and mRNA expressions in dose and time dependent manner." (PMID 24637722, 2014). "In this study, we found that CCN2 enhanced resistance to cisplatin-increasing cell death in human osteosarcoma in vivo and in vitro." (PMID 24637722, 2014). "The results also showed that CCN2 protected doxorubicin-induced cell death in human osteosarcoma cells." (PMID 24637722, 2014). "Overexpression of CCN2 also increased survivin expression in human osteosarcoma." (PMID 24637722, 2014). "Although the role of CCN2 in chemoresistance has been implicated in some cancer cells, the effect of CCN2 on cisplatin-induced cell apoptosis in human osteosarcoma has not been extensively studied." (PMID 24637722, 2014). "Our results provide evidence that CCN2 might be a novel chemotherapy target in human osteosarcoma cells." (PMID 24637722, 2014). "Therefore, our data suggest that CCN2 might be a critical oncogene of human osteosarcoma for cisplatin-resistance and supported osteosarcoma cell growth in vivo and in vitro." (PMID 24637722, 2014). "However, the signaling pathways in CCN2-mediated chemoresistance in human osteosarcoma are mostly unclear and largely unknown." (PMID 24637722, 2014). "Therefore, we hypothesized that CCN2 may be involved in chemotherapy of cisplatin in human osteosarcoma cells." (PMID 24637722, 2014). "Therefore, we hypothesized that CCN2 may promote resistance to cisplatin in human osteosarcoma cells." (PMID 24637722, 2014). "Thus, we conclude that CCN2 might be a critical oncogene and believe these data support an investigation of CCN2 as a strategic target for osteosarcoma therapy." (PMID 24637722, 2014). "CCN1, CCN2, CCN3 and CCN4 are all poorly expressed in healthy adult bony tissues, but they are up regulated in primary samples as well as osteosarcoma cell lines." (PMID 34228239, 2021). "We suggested that CCN2 increased FAK, MEK, and ERK survival signaling pathways and subsequently protected cisplatin-induced cell apoptosis in human osteosarcoma." (PMID 24637722, 2014).
osteosarcoma (continued). "However, the effect of CCN2 in human osteosarcoma is largely unknown." (PMID 24637722, 2014). "Therefore, CCN2 may be a novel chemotherapy target in human osteosarcoma." (PMID 24637722, 2014). "First, we treated osteosarcoma cell lines (MG-63, HOS, and U-2 OS) with cisplatin and examined CCN2 expression." (PMID 24637722, 2014). "CCN1 and CCN2 do not promote osteosarcoma cell proliferation per se but protect cells from apoptosis and decrease chemotherapeutic efficacy." (PMID 34228239, 2021). "However, overexpression of CCN2 did not affect basal cell proliferation in human osteosarcoma cells." (PMID 24637722, 2014).
colorectal cancer (36 papers, 2007 to 2025). A primary or metastatic malignant neoplasm that affects the colon or rectum. "Furthermore, to strengthen the association between CCN2 expression and cancer stemness, we performed functional assays using colorectal cancer cell lines to assess stem cell properties and tumorigenic potential according to CCN2 expression levels." (PMID 41303528, 2025). "Considering the strong association between CCN2 expression and the CMS4 colorectal cancer subtype, CCN2 could be an interesting target for therapy." (PMID 27613407, 2016). "To confirm that PDE4D promotes colorectal cancer metastasis by upregulating CCN2, we performed immunofluorescence (IF) in PDE4D inhibitor (roflumilast) treated MC38 cells." (PMID 39956959, 2025). "Collectively, these results demonstrate that CCN2 promotes proliferation, migration, invasion, and oxaliplatin resistance in colorectal cancer cells, highlighting its potential as a therapeutic target." (PMID 41303528, 2025). "For example, CCN2 inhibits metastasis and invasion in lung adenocarcinoma and colorectal cancer, and CCN2 expression in cancer specimens correlates with relatively early-stage disease or better overall survival." (PMID 29029514, 2017). "This review discusses the available literature on the role of CCN2 in colorectal cancer, with a focus on the ‘fibrotic subtype’ CMS4." (PMID 27613407, 2016). "The available data on the role of CCN2(/CTGF) in colorectal cancer progression and prognosis is limited, and in part contradictory." (PMID 27613407, 2016). "In colorectal cancer, patients showed better overall survival when tumors displayed higher CCN2 expression." (PMID 24637722, 2014). "Alterations to the protein level of CCN2 in colorectal cancer cell lines also negatively modulated their invasive ability." (PMID 24637722, 2014). "Based on these observations, we postulated that CCN2 might contribute to colorectal cancer progression, especially in the CMS4 subtype." (PMID 27613407, 2016). "The high expression of CCN2(/CTGF)x in CMS4 colorectal cancer and its established role in tissue fibrosis warrant further investigation to establish the possible value of xCCN2(/CTGF) as a marker and potential therapeutic target in CRC, especially in the aggressive mesenchymal subtype." (PMID 27613407, 2016). "It has also been suggested that CCN2 expression contributes to therapy resistance in CRC, since overexpression of CCN2 induced resistance to radiotherapy (combined with simvastatin) in colorectal cancer cell lines, whereas CCN2 knockdown increased the radiosensitivity." (PMID 27613407, 2016). "Notably, it has recently been postulated that CCN2/CTGF might contribute to colorectal cancer progression, especially in a fibrotic consensus molecular subtype." (PMID 32260433, 2020). "Additionally, CCN2 promotes the epithelial–mesenchymal transition (EMT), angiogenesis, and stroma infiltration in colorectal cancer and enhances proliferation, migration, and invasion in urothelial bladder cancer." (PMID 40724877, 2025).
Hypertension (34 papers, 2012 to 2026). The presence of chronic increased pressure in the systemic arterial system. "Hence CCN2 has been associated with and used as a marker in conditions with high tissue stiffness such as various organ fibrosis, atherosclerosis and hypertension." (PMID 33662577, 2021). "Furthermore, there is a progressive increase in Ang-II and CCN2/CTGF levels that positively correlates with the degree of hypertension (blood pressure values) in patients." (PMID 34063397, 2021). "Additionally, high levels of CCN2 were associated with treated hypertension and higher body mass index, but these findings were not consistent across the two populations." (PMID 28931920, 2017). "CCN2/CTGF levels were also remarkably elevated in lung and vasculature in various experimental models of hypertension." (PMID 32429045, 2020). "Of particular significance, the CCN2/CTGF gene was strongly up-regulated in mechanically challenged organs as a result of various etiologies (e.g., hypertension, hemodynamics, matrix stiffness, metabolic injury, and obstruction)." (PMID 32429045, 2020). "To verify the essential role of CCN5 in hypertension, firstly we detected decreased CCN5 levels, but elevated CCN2 levels in all hypertensive patients." (PMID 33013358, 2020).
keloid (34 papers, 2007 to 2025). An irregularly shaped, elevated mark on the skin caused by deposits of excessive amounts of collagen during wound healing. "In addition, the specialized cases of abnormal scarring (e.g., keloids), which apparently develop in regions of the body that are subjected to relatively higher mechanical strains than others, were highly enriched in CCN2/CTGF." (PMID 32429045, 2020).
lung carcinoma (32 papers, 2007 to 2025). "High expression of MMP3 and CCN2/CTGF were prognostically unfavorable in lung cancer and head and neck cancer." (PMID 32260433, 2020). "Furthermore, CCN2 has been demonstrated to block lung cancer development by inhibiting the anoikis pathway related to DAPK36." (PMID 38238592, 2024). "GSTM2 has shown the ability to increase the expression of CCN2 and inhibit lung cancer migration." (PMID 33282950, 2020). "Additionally, CCN2 suppresses lung cancer progression through anoikis pathways involving DAPK." (PMID 39391236, 2024). "Moreover, CCN2 was proved to block lung cancer development via the DAPK-related anoikis pathway." (PMID 34992654, 2021). "In lung cancer, there are many reports indicating that the CCN1 and CCN2 are negatively correlated with the prognosis of lung cancer, where the expression of CCN1 and CCN2 level is lower compared with normal matched lung tissues." (PMID 33105556, 2020).